KRTAP12-3 (keratin associated protein 12-3)
Description:
In the hair cortex, hair keratin intermediate filaments are embedded in an interfilamentous matrix, consisting of hair keratin-associated proteins (KRTAP), which are essential for the formation of a rigid and resistant hair shaft through their extensive disulfide bond cross-linking with abundant cysteine residues of hair keratins. The matrix proteins include the high-sulfur and high-glycine-tyrosine keratins.
Synonyms: KRTAP12.3
Tractability: No criterion of Open Targets' tractability assessment is met for any kind of drug.
Gene: Protein-coding gene on chromosome 21 (44,657,932 to 44,658,341, forward strand). Ensembl gene ENSG00000205439.
Pathways (Reactome):
Developmental Biology: Keratinization
Gene Ontology:
Molecular function: identical protein binding; protein binding
Cellular component: cytosol
Genetic constraint (gnomAD): Loss-of-function variants: 4 observed, 1.6 expected, observed/expected ratio (o/e) 2.5. That is too few expected variants to judge how well the gene tolerates losing a copy. Missense variants: 116 observed, 133.52 expected, observed/expected ratio (o/e) 0.87, 90% interval 0.75 to 1.01. Synonymous variants: 61 observed, 56.48 expected, observed/expected ratio (o/e) 1.08, 90% interval 0.88 to 1.34.
Homologues: Orthologues: chimpanzee KRTAP12-3 (96% identical), rat LOC120098854 (47% identical), rat Krtap10-1 (45% identical), mouse Gm49918 (44% identical), mouse Krtap10-29 (44% identical), mouse Krtap10-31 (44% identical), mouse Krtap10-33 (44% identical), rat Krtap10-9 (44% identical), mouse Krtap10-21 (43% identical), mouse Krtap10-22 (43% identical), mouse Krtap10-25 (43% identical), mouse Krtap10-26 (43% identical), and 14 more. Paralogues in human: KRTAP12-1 (76% identical), KRTAP12-2 (70% identical), KRTAP16-1 (49% identical), KRTAP10-9 (48% identical), KRTAP10-12 (45% identical), KRTAP10-4 (44% identical), KRTAP10-5 (44% identical), KRTAP10-11 (42% identical), KRTAP10-2 (42% identical), KRTAP10-8 (42% identical), KRTAP10-7 (41% identical), KRTAP10-1 (40% identical), and 35 more.